DAGLA (diacylglycerol lipase alpha)
Description:
Serine hydrolase that hydrolyzes arachidonic acid-esterified diacylglycerols (DAGs) to produce the principal endocannabinoid, 2-arachidonoylglycerol (2-AG). Preferentially hydrolyzes sn-1 fatty acids from diacylglycerols (DAG) that contain arachidonic acid (AA) esterified at the sn-2 position to biosynthesize 2-AG. Has negligible activity against other lipids including monoacylglycerols and phospholipids. Plays a key role in regulating 2-AG signaling in the central nervous system (CNS). Regulates 2-AG involved in retrograde suppression at central synapses. Supports axonal growth during development and adult neurogenesis. Plays a role for eCB signaling in the physiological regulation of anxiety and depressive behaviors. Also regulates neuroinflammatory responses in the brain, in particular, LPS-induced microglial activation (By similarity).
Synonyms: C11orf11; KIAA0659; NSDDR; DAGLALPHA; DAGL(ALPHA); NOC2
Tractability: Small molecule: a high-quality ligand is known; it belongs to a druggable protein family. Antibody: UniProt places it where antibodies can reach, with high confidence; its Gene Ontology location is reachable by antibodies, with high confidence; UniProt predicts a signal peptide or a membrane-spanning region. PROTAC: ubiquitination databases record sites on it; its protein half-life has been measured; a small molecule that binds it is known.
Target class: Enzyme; Hydrolase
Chemical probes: LEI-106
Gene: Protein-coding gene on chromosome 11 (61,680,391 to 61,747,003, forward strand). Ensembl gene ENSG00000134780.
Subcellular location: Cell membrane; Postsynaptic density membrane; Early endosome membrane; Cell projection, dendritic spine membrane
Pathways (Reactome):
Hemostasis: Arachidonate production from DAG
Gene Ontology:
Molecular function: protein binding; lipoprotein lipase activity; monoacylglycerol lipase activity; diacylglycerol lipase activity; hydrolase activity
Biological process: arachidonate metabolic process; diacylglycerol catabolic process; retrograde trans-synaptic signaling by endocannabinoid; neurogenesis; regulation of neuroinflammatory response; lipid metabolic process; response to ethanol
Cellular component: dendrite membrane; early endosome membrane; plasma membrane; postsynaptic density membrane; dendritic spine membrane; postsynaptic membrane; varicosity
Genetic constraint (gnomAD): Loss-of-function variants: 22 observed, 103.03 expected, observed/expected ratio (o/e) 0.21, 90% interval 0.15 to 0.31. The upper end of that interval is the gene's LOEUF score, 0.31, which puts it in group 1 of 6, group 1 being the genes least tolerant of losing a copy. Missense variants: 927 observed, 1,472.2 expected, observed/expected ratio (o/e) 0.63, 90% interval 0.6 to 0.67. Synonymous variants: 578 observed, 644.43 expected, observed/expected ratio (o/e) 0.9, 90% interval 0.84 to 0.96.
Homologues: Orthologues: chimpanzee DAGLA (99% identical), macaque DAGLA (99% identical), pig DAGLA (98% identical), rat Dagla (98% identical), dog DAGLA (98% identical), mouse Dagla (98% identical), guinea pig DAGLA (94% identical), rabbit DAGLA (93% identical), tropical clawed frog dagla (82% identical), zebrafish dagla (66% identical), Caenorhabditis elegans dagl-2 (21% identical). Paralogues in human: DAGLB (22% identical), GOLT1A (3% identical), GOLT1B (3% identical).
Diseases named in the same sentence as DAGLA in open-access papers:
DAGLA is named in the same sentence as 48 diseases in open-access papers, as found by Europe PMC text mining. Sharing a sentence is not in itself a finding about the gene and the disease. The quoted sentences say what the papers report.
Anxiety (19 papers, 2016 to 2025). Intense feelings of nervousness, tension, or panic often arise in response to interpersonal stresses. "The findings from Daglα knock out (KO) mice have clearly shown that a loss of 2-AG adversely affects the emotional state in mice, resulting in enhanced anxiety, stress, fear responses, sociability deficits, and impaired exploratory drive." (PMID 36142165, 2022). "Additionally, as the major protein for the synthesis of eCB, loss of DAGLα facilitates anxiety in mice." (PMID 34950028, 2021). "As expected, using our new virus and strategy, we found that specific knockout of DAGLα in aBLA–vHPC circuits promoted anxiety avoidance." (PMID 40522172, 2025). "The eCB signaling system is widely expressed in the brain and plays a key role in the regulation of social and emotional behaviors, as demonstrated by reduced social preference and increased anxiety in global Daglα KO mice." (PMID 40523777, 2025). "Surprisingly, circuit-specific DAGLα knockdown to reduce synaptic eCB release in vAI-PrL and dAI-ovBNST pathways failed to alleviate headache-like cephalic cutaneous allodynia or anxiety-like behaviors." (PMID 41377021, 2025). "Our results, showing that cerebellar PC-specific Daglα KO decreases social preference and increases anxiety, highlight the role of the cerebellum as an important modulator of social behaviors and emotional states." (PMID 40523777, 2025). "Two primary models of DAGLα KO have been significant in studying the effect of 2-AG signalling in stress and anxiety." (PMID 37958825, 2023). "Knockout studies have shown that DAGLA (-/-) mice, which have large reductions in brain 2-AG levels, have increased anxiety-like symptoms." (PMID 33959052, 2021). "Given that DAGLα inhibition can increase unconditioned anxiety, we wanted to rule out the possibility that DO34 increased freezing behavior independent of a fear-conditioning." (PMID 30108473, 2018). "DAGLα−/− mouse models show reduced levels of 2-AG [and in some cases AEA], increases in anxiety associated behaviors and increased susceptibility to adverse behavioral consequences of stress exposures." (PMID 30108473, 2018). "That acute pharmacological DAGL inhibition is associated with impaired extinction of conditioned fear is also globally consistent with the increased unconditioned anxiety and increased stress-susceptibility observed after DAGL inhibition and in DAGLα−/− mice." (PMID 30108473, 2018). "2-AG levels have been reported to drop by ~80% in DAGLA knockout mice, resulting in pronounced anxiety and depression-like behaviors, and increased severity of kainate-induced seizures." (PMID 29145497, 2017). "Although BLA-specific DAGLα deletion minimally impacts baseline anxiety-like behaviours, it increases the proportion of mice showing anxiety-like behaviour after repeated stress exposure and the severity of the anxiety-like phenotype." (PMID 28348378, 2017). "Recent studies in mice indicated that reducing levels of 2-AG by genetic inactivation of the main 2-AG synthesizing enzyme DAGLα lead to a phenotype of increased anxiety and depressive-like behavior." (PMID 27812328, 2016). "However, we also found that DAGLa knockdown in the pBLA‐vHPC pathway reduced anxiety avoidance, which was opposite to those in the aBLA–vHPC pathway." (PMID 40522172, 2025). "However, DAGLa knockdown in the pBLA‐vHPC pathway reduced anxiety avoidance, which was opposite to those in the aBLA–vHPC pathway." (PMID 40522172, 2025). "In contrast, mice with PFC or NAc DAGLα deletion did not exhibit differential susceptibility to acute stress-induced anxiety-like behaviour or adaptation to repeated stress, relative to GFP-injected controls." (PMID 28348378, 2017). "Alternatively, other brain regions besides those tested may be more critical for the modulation of acute stress-induced anxiety or compensatory changes could occur in the weeks after DAGLα deletion that counteract potential increases in acute stress-susceptibility." (PMID 28348378, 2017).
Anxiety (continued). "Our previous results also showed that pharmacological inhibition of DAGLα by intraperitoneal injection of LEI‐106 induced headache‐like behaviours of periorbital allodynia, photophobia and anxiety in Sprague–Dawley rats." (PMID 39827410, 2025). "Along the same line, 2-AG has also been shown to play a role in the reduction of stress induced-anxiety in a role mediated through the actions of MAGL and DAGLA." (PMID 33959052, 2021). "Our study shows that the reduction of cerebellar Daglα contributes to the symptoms of reduced social preference and anxiety (we did not document seizures or ataxia in our KO mice at the ages examined)." (PMID 40523777, 2025). "DAGLα, NAPE-PLD and FAAH expression were also reduced in the prefrontal cortex and hippocampus in S1 mice, brain areas which are also important mediators of fear regulation and anxiety." (PMID 36081934, 2022). "DAGLα inhibition did not reduce voluntary movement or induce anxiety in the open field and elevated plus maze tests, two assays shown to assess behavioral distress, suggesting that acute DAGLα is not necessary for these behaviors." (PMID 33584293, 2020). "Selective DAGLα inhibition induced significant photophobia as measured by the light-dark box, without anxiety like behaviors or changes in voluntary movement." (PMID 33584293, 2020). "Selective inhibition of DAGLα, but not DAGLβ, induced significant periorbital allodynia in a dose-dependent manner, accompanied with increased secondary behavioral measures of distress (i.e., head pressing) and photophobia, but not reduced movement or anxiety." (PMID 33584293, 2020). "Interestingly, genetic deletion of MAGL in mice induced an anxiety-like phenotype, whereas mice lacking DAGLα showed a high anxiety-like phenotype, strengthening the critical involvement of 2-AG in emotional regulation." (PMID 32395111, 2020). "DAGLα deletion within the PFC or NAc did not affect basal anxiety-like behaviours." (PMID 28348378, 2017).
Headache (5 papers, 2020 to 2025). Cephalgia, or pain sensed in various parts of the head, not confined to the area of distribution of any nerve. "Finally, this model of headache via DAGLα inhibition revealed that loss of 2-AG within the PAG is necessary for induction of headache pain." (PMID 33584293, 2020). "In the current paper, we investigated if similar changes in the BBB can be detected in the headache model induced by DAGLα inhibition." (PMID 39827410, 2025). "In our previous paper, we showed that intraperitoneal administration of the DAGLα inhibitor LEI‐106 induced headache‐like symptoms, including cutaneous allodynia at the cephalic site, and spontaneous pain behaviour, like head‐pressing and photophobia." (PMID 39827410, 2025). "Preclinical models of cortical spreading depression opioid- and sumatriptan-induced headache (MOHs), and acute inhibition of DAGLA showed reduced 2-AG in the periaqueductal gray (PAG) at time points associated with periorbital allodynia." (PMID 39563240, 2024). "DAGLα inhibition induced both head-tucking and photophobia, indicating both distress and visual sensitivity, characteristics of clinical headache." (PMID 33584293, 2020). "Together, these data support 1) DAGLα inhibition as a non-invasive model of episodic headache and 2) identify the 2-AG-ECS system within the PAG as necessary for headache pathology." (PMID 33584293, 2020). "Responsivity to the acute dosing of abortive antimigraine agents, sumatriptan and olcegepant were used to validate DAGLα inhibition as a non-invasive, preclinical model of headache." (PMID 33584293, 2020). "Thus, pathological reductions in the functional expression of DAGLα in females during pain states, including headache, may have a pronounced impact via decreased 2-AG signaling." (PMID 34749819, 2021). "The current study presents an original protocol for inducing headache-like pain by depletion of endocannabinoid tone, using non-selective DAGL and selective DAGLα inhibitors." (PMID 33584293, 2020).
Obesity (5 papers, 2016 to 2023). Accumulation of substantial excess body fat. "No human studies were identified that examined associations between DAGLA gene variants and obesity." (PMID 34959715, 2021). "Recent studies have implicated DAGLα as an emerging drug target for several conditions including pain and obesity." (PMID 27013337, 2016). "This is in accordance with the assumption of a generally higher activation of the eCB system in conditions of overnutrition and obesity, and increased DAGLα expression was also shown in subcutaneous tissue of obese human subjects." (PMID 28859076, 2017). "Human studies evaluating associations between DAGLA (and possibly also DAGLB) variants and obesity may provide some additional insight into whether modulating 2-AG synthesis impacts obesity-related outcomes." (PMID 34959715, 2021). "Therefore, the development of selective DAGLα inhibitors is of interest in reducing endocannabinoid tone in obesity, a statement supported by pharmacological manipulation of DAGLα in DIO models." (PMID 34718828, 2021). "A review of these data found no SNPs in FAAH, MGLL, or DAGLA/DAGLB that showed genome-wide significant association (p < 5 × 10−8) with obesity or related outcomes (no SNPs in CNR1 either)." (PMID 34959715, 2021). "Based on a handful of animal studies, inhibition of DAGLα may be a promising strategy to treat obesity." (PMID 34959715, 2021). "scWAT gene expression of SLC27A2, CNR1, DAGLA, MGLL, FAAH, SLC27A1 and SLC27A2 were lower in individuals living with healthy obesity." (PMID 38024342, 2023). "Accordingly, PLA2G2A and PLA2G4A genes were up-regulated by omega-3 polyunsaturated fatty acids supplementation, whereas SLC27A2, CNR1, DAGLA, MGLL, FAAH, SLC27A1, and SLC27A2 genes were found to be down-regulated in people living with healthy obesity." (PMID 38024342, 2023).
migraine (4 papers, 2017 to 2024). "Here, we found that MD in resistant migraine was associated with lower mRNA levels of CB2 and DAGLα in peripheral cells than wMD." (PMID 38339171, 2024). "Therefore, symptoms observed after the acute pharmacological blockade of DAGLα more likely represent the episodic stage of migraine-like pain." (PMID 33584293, 2020). "Importantly, female rats showed greater sensitivity to DAGLα inhibition as compared to males mirroring sex differences in the clinical presentation of migraine." (PMID 33584293, 2020). "Whether chronic administration of DAGLα inhibitor could capture signs of chronic form of migraine is an exciting question that needs to be addressed in future experiments." (PMID 33584293, 2020). "Furthermore, there is evidence that depletion of 2-AG via inhibition of DAGLα may be sufficient to trigger migraine-like pain in animals." (PMID 34749819, 2021). "Together, these data suggest DAGLα inhibition produces migraine-like behaviors of allodynia and photophobia without reducing voluntary movement or acting as an anxiogenic." (PMID 33584293, 2020).
autism (3 papers, 2017 to 2025). Persistent deficits in social interaction and communication and interaction as well as a markedly restricted repertoire of activity and interest as well as repetitive patterns of behavior. "For instance, rare heterozygous variants in the diacyl glycerol lipase A (DAGLA) gene encoding diacylglycerol lipase alpha were significantly associated with seizures and neurodevelopmental disorders, including autism and abnormalities of brain morphology." (PMID 35563156, 2022). "Similarly, heterozygous rare variants in DAGLA, which encodes diacylglycerol lipase alpha, were found to be significantly associated with seizures and neurodevelopmental disorders, including autism and abnormalities of brain morphology, compared to controls." (PMID 29145497, 2017).
epilepsy (3 papers, 2015 to 2025). A brain disorder characterized by episodes of abnormally increased neuronal discharge resulting in transient episodes of sensory or motor neurological dysfunction, or psychic dysfunction. "In 35 pediatric patients (out of 6,032 probands with neurodevelopmental disorder diagnosis), a significant association was found between rare heterozygote variants in DAGLα and ASD, seizure disorders, and ataxia." (PMID 40523777, 2025). "A 2017 publication identified 35 individuals with rare genetic variants in DAGLα (the majority of the mutations were identified in the C-terminal tail of DAGLα) diagnosed with ASD, developmental delays, movement disorders, ataxia, and seizure disorders." (PMID 40523777, 2025).
Spinocerebellar Ataxia (3 papers, 2023 to 2025). "A recent study focused on nine idiopathic pediatric patients with mutations in DAGLα and a specific set of symptoms: ataxia, nystagmus, and developmental delay." (PMID 40523777, 2025).
colitis (2 papers, 2009 to 2021). Inflammation of the colon. "We only found a rise of DAGLα expression in acute moderate colitis compared with control groups [61.21±3.20 vs 53.28±1.16 (×103); p<0.05]." (PMID 19730730, 2009). "In mild colitis patients, higher levels of DAGLα were also observed in quiescent samples compared with controls [55.67±2.93 vs 53.28±1.16 (×103); p<0.05]." (PMID 19730730, 2009).
developmental delay (2 papers, 2017 to 2025). "Only two of the 35 samples with rare DAGLA variants harbored a likely pathogenic variant in another gene known to be associated with seizures and developmental delay (GRIN2A in subject 061 and MEF2C in subject 044)." (PMID 29145497, 2017).
fragile X syndrome (2 papers, 2021 to 2025). A genetic syndrome caused by mutations in the FMR1 gene which is responsible for the expression of the fragile X mental retardation 1 protein. "Interestingly, these changes mirror those observed in the mouse model of Fragile X syndrome, where FMR1 knockout increased striatal DAGLα and MAGL expression." (PMID 33931678, 2021).
lung carcinoma (2 papers, 2018 to 2021). "The SNP rs60507107 is correlated with increased risk of lung cancer, as the A allele reduces the binding affinity of CTCF at a CTCF binding site in the first intron of DAGLA (in 11q12.2), leading to its altered expression in lung cancer." (PMID 34449663, 2021).
alcoholism (1 paper, 2021). "The GMDR analysis suggests that a certain combination of SNPs along the CNR1-DAGLA-MGLL genes protect against or pose a risk for alcoholism, by presumably modulating DAGLA and or MGLL expression and subsequently 2-AG levels." (PMID 33959052, 2021). "The study by Ishiguro and colleagues was also the first to link SNPs in the DAGLA gene and alcoholism in humans." (PMID 33959052, 2021).
attention deficit-hyperactivity disorder (1 paper, 2019). A disorder characterized by a marked pattern of inattention and/or hyperactivity-impulsivity that is inconsistent with developmental level and clearly interferes with functioning in at least two settings (e.g. at home and at school). "Other hub genes (GABBR2, GRM7, MEF2C, SCN2A, KMT2C, and DAGLA) dysfunction have been reported to contribute to ASD and other psychiatric disorders such as Attention-Deficit Hyperactivity Disorder (ADHD), Huntington’s disease, and Rett-syndrome." (PMID 31649562, 2019).
bladder cancer (1 paper, 2020). "To better understand the role of ECs and NAEs in bladder cancer, we analyzed gene expression data from TGCA database regarding the metabolic pathway of the ECS, comprising the synthetic enzymes (PLCB1-4, PTPN22, ABHD4, GDE1, DAGLA, DAGLB, and NAPE-PLD) and the hydrolytic ones (FAAH, NAAA, and MGLL)." (PMID 32260109, 2020).
breast carcinoma (1 paper, 2019). "Database analysis identified the downregulation of DAGLA in breast cancer tissue compared to normal tissues." (PMID 31847101, 2019). "In addition, breast cancer patients with higher expression of DAGLA showed better prognosis than those with lower expression, suggesting DAGLA as a tumor suppressor in breast cancer." (PMID 31847101, 2019).
Hypoglycemia (1 paper, 2019). A decreased concentration of glucose in the blood. "In hypoglycemia (4.5 ± 0.5 mM), a slight reaction by DAGLα was detected and mainly localized in the ventricular area (tanycytes) and only in very few parenchymal cells of the ARC." (PMID 31620093, 2019).